RAD54B (RAD54 homolog B)
Description:
Multifunctional ATPase that could play with RAD54, a redundant role in homologous recombination (HR), a major pathway for repairing DNA double-strand breaks (DSBs), single-stranded DNA (ssDNA) gaps, and stalled or collapsed replication forks. Could act as a molecular motor during the homology search and guide RAD51 ssDNA along a donor dsDNA thereby changing the homology search from the diffusion-based mechanism to a motor-guided mechanism. Once DNA strand exchange occured, could dissociate RAD51 from nucleoprotein filaments formed on dsDNA (By similarity).
Synonyms: RDH54
Tractability: PROTAC: ubiquitination databases record sites on it.
Gene: Protein-coding gene on chromosome 8 (94,371,960 to 94,475,133, reverse strand). Ensembl gene ENSG00000197275.
Subcellular location: Nucleus, nucleoplasm
Subcellular location (Human Protein Atlas): Cytosol; Nucleoplasm
Gene Ontology:
Molecular function: ATP hydrolysis activity; ATP-dependent activity, acting on DNA; DNA translocase activity; protein binding; protein-macromolecule adaptor activity; ATP binding
Biological process: double-strand break repair via homologous recombination; homologous recombination; reciprocal meiotic recombination
Cellular component: nucleoplasm; site of double-strand break; nucleus
Genetic constraint (gnomAD): Loss-of-function variants: 66 observed, 82.41 expected, observed/expected ratio (o/e) 0.8, 90% interval 0.66 to 0.98. The upper end of that interval is the gene's LOEUF score, 0.98, which puts it in group 4 of 6, group 1 being the genes least tolerant of losing a copy. Missense variants: 862 observed, 1,008.7 expected, observed/expected ratio (o/e) 0.85, 90% interval 0.81 to 0.9. Synonymous variants: 309 observed, 345.27 expected, observed/expected ratio (o/e) 0.89, 90% interval 0.81 to 0.98.
Homologues: Orthologues: chimpanzee RAD54B (99% identical), macaque RAD54B (97% identical), pig RAD54B (86% identical), rabbit RAD54B (86% identical), dog RAD54B (85% identical), guinea pig RAD54B (84% identical), mouse Rad54b (78% identical), rat Rad54b (72% identical), tropical clawed frog rad54b (62% identical), zebrafish rad54b (53% identical), Caenorhabditis elegans rad-54.B (29% identical). Paralogues in human: RAD54L (35% identical), CHD5 (22% identical), CHD4 (22% identical), SMARCA2 (22% identical), CHD3 (21% identical), SMARCA4 (21% identical), ERCC6 (21% identical), RAD54L2 (20% identical), TTF2 (20% identical), CHD7 (20% identical), CHD9 (20% identical), BTAF1 (20% identical), and 18 more.
Diseases named in the same sentence as RAD54B in open-access papers:
RAD54B is named in the same sentence as 31 diseases in open-access papers, as found by Europe PMC text mining. Sharing a sentence is not in itself a finding about the gene and the disease. The quoted sentences say what the papers report.
colorectal cancer (11 papers, 2013 to 2025). A primary or metastatic malignant neoplasm that affects the colon or rectum. "For example, the selective killing of RAD54B-deficient colorectal cancer cells by PARP1 inhibitors is enhanced by silencing SOD1." (PMID 40001471, 2025). "RAD54B-deficient colorectal cancer cells were reported to increase accumulation of DNA DSBs and apoptosis under olaparib treatment." (PMID 35952757, 2022). "SL has been observed in a RAD54B-deficient human colorectal cancer cell line following iatrogenic reduction of FEN1 expression." (PMID 26431531, 2015). "PARP1 inhibition along with superoxide dismutase 1 (SOD1) inhibition could promote the synthetic lethal killing of RAD54B-deficient colorectal cancer cells." (PMID 32711558, 2020). "Based on these findings, SOD1 inhibition was proposed as a novel therapeutic approach for colorectal cancers with RAD54B defects." (PMID 40001471, 2025). "The human genes SMC1, SMC3, NIPBL, STAG3, RNF20, FBXW7/CDC4, MRE11A, RAD54B and BLM have been found to be mutated in colorectal cancer, and together account for approximately 25% of the CIN mutational spectrum of this disease." (PMID 23382697, 2013). "Moreover, in colorectal cancer cells, inactivation of RAD54B was reported to increase DSBs and apoptosis." (PMID 35952757, 2022). "Using siRNA-based silencing and high-content imaging they showed that diminished FEN1 (flap endonuclease 1) expression induced cellular selective cytotoxicity within RAD54B-deficient colorectal cancer cell but not in isogenic control cell line." (PMID 24202319, 2013). "Additional studies have shown that increases in reactive oxygen species following SOD1 (Superoxide Dismutase 1) silencing and inhibition induces SL killing in colorectal cancer cells harboring defects in established CIN genes, like RAD54B, BLM, and CHEK2." (PMID 29104272, 2017).
breast carcinoma (10 papers, 2018 to 2024). "For instance, upregulation of RAD54B indicates a poor survival of patients with luminal A subtype breast cancer, thus knockdown of RAD54B inhibits the growth of luminal A subtype breast cancer both in vitro and in vivo." (PMID 38378037, 2024). "In fact, alterations of RAD54B have been detected in several cancers, including lung adenocarcinoma, breast cancer, and hepatoma." (PMID 35952757, 2022). "The association of high RAD54B expression with LNM in breast cancer (BRCA) and cholangiocarcinoma and its prognostic effect in BRCA LNM cases suggest the value of RAD54B at the pancancer level." (PMID 35847584, 2022). "In turn, it was found in breast cancer cells that miR-215-5p targets mRNA encoding RAD54 Homolog B (RAD54B), which is involved in homologous recombination repair of DNA breaks, thus inhibiting proliferation and promoting apoptosis of MCF-7 breast cancer cells." (PMID 35922756, 2022). "On the other side, RAD54B is a telomere-related gene involved in DNA repair process, and coding-missense changes of this gene have been found in familial breast cancer cases not explained by mutations in the best-known high susceptibility genes BRCA1 and BRCA2." (PMID 30211214, 2018). "Down-regulation of miR-192/215-5p are generally found in cancers of various types, and in breast cancer it results in an increase in the levels of AKT protein kinase and DNA repair and recombination protein RAD54B." (PMID 35922756, 2022). "Some important breast cancer and tumor oncogenes, such as PARI, CCNE2 and RAD54B, were detected to have positive correlations with epithelial tissue proportion in our study." (PMID 33371906, 2020).
lung adenocarcinoma (4 papers, 2015 to 2022). A carcinoma that arises from the lung and is characterized by the presence of malignant glandular epithelial cells. "In lung adenocarcinoma, simultaneous expression of RAD54B and FEN1 proteins was also associated with late-stage LNM in patients." (PMID 35847584, 2022). "RAD54B protein expression is significantly higher in lung adenocarcinoma tissues than that in healthy lung tissues, and inhibition of RAD54B expression in A549 cells can significantly reduce cell proliferation and increase apoptotic rate." (PMID 36384536, 2022). "Among 24 paired genes, only FEN1 (Flap endonuclease 1) and RAD54B (RAD54 homolog B) were overexpressed in lung adenocarcinoma patients with poor prognosis." (PMID 26431531, 2015). "We further examined the role of FEN1 and RAD54B in the prognosis of lung adenocarcinoma patients by analyzing the clinical outcome with respect to gene expression levels." (PMID 26431531, 2015). "Relationships of FEN1 and RAD54B expression with clinical parameters in lung adenocarcinoma patients." (PMID 26431531, 2015). "Univariate and multivariate analysis of FEN1 and RAD54B in lung adenocarcinoma patients." (PMID 26431531, 2015). "In present study, the overexpression of FEN1 and RAD54B in poorly prognostic lung adenocarcinoma suggests that these two genes might be potential markers for selecting patients at high risk and could be used in the development of effective personalized therapy." (PMID 26431531, 2015).
melanoma (4 papers, 2015 to 2024). A malignant, usually aggressive tumor composed of atypical, neoplastic melanocytes. "Based on this, we could not identify any evidence supporting the disease-modifying role of the germline RAD54B c.337A > G p.Lys113Glu variant regarding the unfavorable outcome, progression of malignant melanoma, or resistance to immunotherapy." (PMID 39795882, 2024). "Additionally, variants of FANCI, PALB2, and RAD54B are associated with altered survival outcomes in melanoma patients." (PMID 39795882, 2024). "However, we identified three novel variants in the Fanconi anemia, complementation group I gene (FANCI) in three patients (patients 9, 15, and 16), and one novel variant in the RAD54 homolog B gene (RAD54B) in one melanoma patient (patient 14)." (PMID 39795882, 2024). "Here, our aim was to investigate whether patients in the Hungarian melanoma cohort (n = 17) with increased risk carry any pathogenic or likely pathogenic germline variants of the BRCA2, POLE, WRN, FANCI, PALB2, and RAD54B genes associated with melanoma survival and response to therapy." (PMID 39795882, 2024). "The germline variants of BRCA2, POLE, WRN, FANCI, PALB2, and RAD54B genes, involved in DNS repair mechanisms, have been implicated in rendering melanoma patients more susceptible to tumor progression and affecting their response to treatments." (PMID 39795882, 2024). "Although RAD54B, BLM and CHEK2 genes are mutated in CRC, they are also mutated in numerous additional cancers including pancreatic (~16.5% collectively), prostate (~16.7%), melanoma (~15.1%) and endometrial (~8.8%)." (PMID 26318585, 2015).
hepatoma (3 papers, 2022 to 2024). "In hepatoma cell lines, RAD54B was significantly higher expressed than in normal hepatocytes." (PMID 35847584, 2022).
liver cancer (3 papers, 2021 to 2022). An epithelial or non-epithelial malignant neoplasm that arises from the liver. "In this study, the immunohistochemical results in the HPA database showed that RAD54B is weakly expressed in liver cancer patients, while its gene mutation rate is high (16%)." (PMID 36531219, 2022). "Moreover, high expression of RAD54B protein in liver cancer tissues was significantly associated with poor prognosis." (PMID 35847584, 2022). "Studies have reported that RAD54B can promote the metastatic properties of liver cancer cells through the Wnt/β-catenin signaling axis." (PMID 35847584, 2022). "In addition, inhibiting RAD54B can inhibit the proliferation of liver cancer cells and promote cell apoptosis." (PMID 33635591, 2021).
cervical cancer (2 papers, 2016). A primary or metastatic malignant neoplasm involving the cervix. "PMS1, RAD54B, FAAP20 and BRCA1 exhibited almost uniform hyper- or hypomethylation in the cervical cancer samples." (PMID 27683114, 2016).
colon cancer (2 papers, 2015 to 2021). "Homozygous mutations in highly conserved positions of RAD54B have been found in human primary lymphoma and colon cancer." (PMID 33635591, 2021). "Homozygous mutations and high expression level of this gene were observed in primary colon cancer, suggesting that some cancers arise through alterations of the RAD54B function." (PMID 26431531, 2015).
lung carcinoma (2 papers, 2015 to 2024). "Clinical effect of FEN1 and RAD54B in lung cancer death patients." (PMID 26431531, 2015).
ovarian carcinoma (2 papers, 2022). A malignant neoplasm originating from the surface ovarian epithelium. "Then, we focused on genes traditionally associated with breast/ovarian cancer or other malignancies, and identified 23 missenses, 2 splicing, and 2 UTR variants mainly affecting genes involved in DNA repair, such as RAD51, RAD54B, PMS1, FANCD2, XRCC1, and BLM." (PMID 35893033, 2022).
prostate carcinoma (2 papers, 2015 to 2020). A carcinoma that arises from epithelial cells of the prostate gland. "We verified the results in MCF7 cells by determining the effect of RAD54L+RAD54B depletion in two additional cell lines: the prostate cancer cell line, PC-3 and the triple-negative breast cancer cell line, MDAMB231." (PMID 25765654, 2015).
gastric cancer (1 paper, 2024). A primary or metastatic malignant neoplasm involving the stomach. "Hence, the role and underlying molecular mechanism of RAD54B were explored in gastric cancer in the current study." (PMID 38378037, 2024). "Therefore, both loss-of-function and gain-of-function assays expounded that RAD54B promoted the tube formation of gastric cancer cells." (PMID 38378037, 2024). "Evidence has elucidated that RAD54B exerts a crucial role in the progress of various tumors, but its specific role and mechanism in gastric cancer remain gloomy." (PMID 38378037, 2024). "Both loss-of-function and gain-of-function assays illustrated that RAD54B promoted the growth, mobility, invasion and tube formation of gastric cancer." (PMID 38378037, 2024). "Both loss-of-function and gain-of-function assays demonstrated that RAD54B facilitated gastric cancer cell progress and angiogenesis through the Wnt/β-catenin axis." (PMID 38378037, 2024). "In the current study, the level of RAD54B was discovered to be enhanced in gastric cancer based on the ATGC and GEPIA databases, which was also confirmed in gastric cancer cell lines." (PMID 38378037, 2024). "Based on these outcomes, we concluded that RAD54B facilitated gastric cancer cell progress and angiogenesis through activating the Wnt/β-catenin pathway." (PMID 38378037, 2024). "The role of RAD54B in the growth, migration, invasion and tube formation of gastric cancer was evaluated by Edu, colony formation, transwell and tube formation assays." (PMID 38378037, 2024). "More importantly, in vivo assay also verified that RAD54B accelerated the growth of gastric cancer and Wnt/β-catenin signaling pathway." (PMID 38378037, 2024). "The expression of RAD54B was discovered to be upregulated in gastric cancer based on the ATGC and GEPIA databases, which was also confirmed in gastric cancer cell lines." (PMID 38378037, 2024). "More importantly, in vivo assay also verified that RAD54B accelerated the growth of gastric cancer and activation of Wnt/β-catenin signaling pathway." (PMID 38378037, 2024). "In summary, the results in the current study clarified that RAD54B level was significantly upregulated in gastric cancer." (PMID 38378037, 2024). "In addition, the molecular mechanism of RAD54B in gastric cancer was also determined by western blot." (PMID 38378037, 2024). "Therefore, RAD54B accelerated gastric cancer progress and angiogenesis by activating the Wnt/β-catenin pathway." (PMID 38378037, 2024). "Briefly, RAD54B expression was up-regulated in gastric cancer." (PMID 38378037, 2024). "Thus, these outcomes demonstrated that RAD54B accelerated the proliferation of gastric cancer and activation of Wnt/β-catenin signaling axis in vivo." (PMID 38378037, 2024). "In addition, the effect of RAD54B on the mobility and invasion of gastric cancer was also assessed by transwell assay." (PMID 38378037, 2024). "Upregulated expression of RAD54B indicated that RAD54B might exert a crucial effect during the progress of gastric cancer." (PMID 38378037, 2024). "Furthermore, a prominent increase in RAD54B expression was also observed in the gastric cancer cell lines, including AGS, MKN45, NCI-N87 and HGC-27, relative to that in human gastric epithelial cells GES-1." (PMID 38378037, 2024). "Thus, RAD54B expedited the mobility and invasion of gastric cancer cells." (PMID 38378037, 2024). "Therefore, RAD54B increased the viability of gastric cancer cells." (PMID 38378037, 2024).
hearing loss (1 paper, 2012). "The methylation of TP73, the negative expression of cyclin D1, the positive expression of B7-H1, increased expression of platelet-derived growth factor A, underexpression of PEX5L, RAD54B, and PSMAL, and overexpression of CEA are factors associated with hearing loss and VS." (PMID 22567403, 2012).
lymph node metastasis (1 paper, 2015). "Interestingly, we saw a similar significant correlation between the synergic effect of FEN1 and RAD54B and lymph node metastasis and poor patient survival in our study." (PMID 26431531, 2015).
neuroblastoma (1 paper, 2015). Neuroblastoma (NB) is the most common solid, extracranial childhood tumor. "Among the neuroblastoma genes, RAD54B, BBS9 and UNKL were detected in exosomes while BBS9, IGFN1 and PKD1L3 were identified in ectosomes." (PMID 25944692, 2015).
ovarian tumor (1 paper, 2024). "According to earlier studies, homologous recombination repair is inhibited by RAD54B knockdown, and ovarian tumor tissues with RAD54B mutations have been shown to have more DNA double-strand breaks than normal tissues." (PMID 38735911, 2024).
pheochromocytoma (1 paper, 2025). "Somatic mutations of BRAF and RAD54B were detected in Langerhans cells and EPAS1 in pheochromocytoma." (PMID 40290304, 2025).
stomach adenocarcinoma (1 paper, 2024). "The level of RAD54B in stomach adenocarcinoma (STAD) was significantly increased compared with that in normal samples." (PMID 38378037, 2024).